IDH1 (isocitrate dehydrogenase (NADP(+)) 1)
Diseases named in the same sentence as IDH1 in open-access papers (continued):
Sharing a sentence is not in itself a finding about the gene and the disease.
astrocytic tumor (continued). "Our results also illustrated that high Ki-67 expression was dominant in WT IDH1/2 astrocytic tumors (P<0.05, Chi-Square test), and its relative expression level was significantly different in the three malignancy grades." (PMID 24810474, 2014). "We investigated ATRX mRNA expression and its association with IDH1 and IDH2 mutations in 169 adult astrocytic tumors using whole transcriptome sequencing." (PMID 24810474, 2014). "In 105 astrocytic tumors (Grade II and III), the mean global incidence of IDH1/2 mutation was 46.7%." (PMID 22427879, 2012). "We speculated that IDH1- R132H accompanied by ATRX or Ki-67 may represent a distinct biological process during the development of astrocytic tumors from the original tumor cells." (PMID 27713914, 2016). "In contrast with IDH1/2 mutations and decreased ATRX expression being widely considered as key aberrations in the early stage of astrocytic tumors, increasing Ki-67 expression may be the final event in the progression of these tumors." (PMID 24810474, 2014). "Unlike other, much more established markers in astrocytic tumors, such as the presence of an IDH1/2 mutations, 1p/19q translocation and MGMT mutations, Ki-67 does not seem to be of viable significance in the everyday pathological verification of these oncological entries." (PMID 28845375, 2017). "Excitingly, regardless of histological grading, our new molecular classification model on the basis of IDH1/2 mutational status and ATRX/Ki-67 expression could exactly reflect the biological properties of the three subgroups of astrocytic tumors with distinct clinical prognosis." (PMID 24810474, 2014). "IHC was applied to 75 astrocytic lesions (18 astrogliosis and 57 astrocytic tumors) using antibodies directed against WT1 clone 6F-H2, isocitrate dehydrogenase 1(IDH1), Bcl2 and Ki67." (PMID 32856872, 2020). "Patients with IDH1-R132H positive astrocytic tumors had a better outcome than those with IDH1-R132H negative astrocytic tumors." (PMID 27713914, 2016). "In summary, our results showed that ATRX in cooperation with IDH1/2 and Ki-67 defines three subgroups of astrocytic tumors regardless of the conventional WHO grades consensus." (PMID 24810474, 2014). "In addition, the Ki-67 high expression restricted in the tumors with IDH1- R132H negative, indicating a group astrocytic tumors with high cell proliferative capacity (p=0.0129)." (PMID 27713914, 2016). "In cases of oligoastrocytic tumors, cases showing astrocytic morphology and IDH1 mutant and ATRX retained are more toward oligodendroglial rather than astrocytic tumors, as ATRX and 1p/19q co-deletion are mutually exclusive." (PMID 39192927, 2024). "In accord with previous reports, among the 41 tumor samples with IDH1-R132H positive, 34 lacked ATRX nuclear protein, while 53 samples of 74 astrocytic tumors with IDH1-R132H negative expressed ATRX, indicating a strong association between ATRX loss and IDH1-R132H (p<0.0001, Chi-Square test)." (PMID 27713914, 2016). "We observed that patients with IDH1-R132H positive astrocytic tumors had a longer progressive-free survival (PFS) than those with IDH1- R132H negative astrocytic tumors (Median PFS of IDH1-R132H positive=802 days, Median PFS of IDH1-R132H negative=461.5 days; p<0.0001)." (PMID 27713914, 2016).
cartilaginous tumors (30 papers, 2012 to 2025). "IDH mutations are involved in the pathogenesis and prognosis of a variety of neoplasms, and recently, IDH1/2 mutations have been found in cartilage tumors." (PMID 38170705, 2024). "Some tumor types show highly specific alterations like synovial sarcoma (SS18::SSX fusions) and chondroblastoma (H3-3B mutations), other mutations are found in tumor subgroups such as IDH1/2 mutations in cartilage neoplasms." (PMID 38231260, 2024). "IDH1/IDH2 mutations in cartilage tumors were associated with an aberrant epigenome, leading to global hypermethylation and downregulated expression of genes." (PMID 36926116, 2023). "Grade 1 tumors often have mutations in the SDH gene family (central atypical cartilaginous tumors mostly IDH1 and 2, secondary peripheral atypical cartilaginous tumors mostly EXT1)." (PMID 35681674, 2022). "Isocitrate dehydrogenase (IDH1/2) gene mutations are the most frequently observed mutations in cartilaginous tumors." (PMID 33413208, 2021). "IDH-1 or -2 are frequently mutated in malignant cartilaginous tumours and two phase I clinical trials are in progress with AG-120, a mutant IDH-1 inhibitor (NCT02073994) and AG-221, a mutant IDH2 inhibitor (NCT02273739)." (PMID 29238848, 2018). "The incidence of IDH1/2 mutations in cartilaginous tumors was previously shown to be the highest among various types of tumors, except for those in the central nervous system." (PMID 26161668, 2015). "In 2011, cartilaginous tumors were added to the list of tumors with IDH1 mutations as tumors with the highest frequency IDH mutations, except for central nervous system tumors." (PMID 26161668, 2015). "Somatic mosaic IDH1/2 mutations are also reported in Ollier disease and Maffucci syndrome, which are characterized by multiple central cartilaginous tumors." (PMID 24403254, 2013). "However, here, we additionally reported the first case of Ollier disease with an ovarian tumour, which harboured the identical IDH1 mutation with the corresponding cartilaginous tumour." (PMID 36428825, 2022). "Also, the cartilaginous tumors and other neoplasms with IDH1/2 mutations have increased levels of R-2HG." (PMID 33413208, 2021). "Cartilage tumors frequently harbor mutations in the isocitrate dehydrogenase (IDH1 or IDH2) genes." (PMID 33266275, 2020). "Our results are in line with the hypothesis that mutations in IDH1 or -2 are early events in the development of cartilaginous tumors." (PMID 26046462, 2015). "Indeed, increased levels of D-2-HG have been found in cartilage tumors with an IDH1 or IDH2 mutation, and DNA hypermethylation was shown in enchondromas with an IDH1/2 mutation." (PMID 25895133, 2015). "Results showed that mutations of H3F3A were detected in all giant cell tumor of bone and malignant giant cell tumor of bone, and mutations of IDH1/2 (including 10 IDH1 and 5 IDH2) were detected in chondrogenic tumors." (PMID 35756627, 2022). "Isocitrate dehydrogenase type 1 (IDH1) and IDH2 mutations are present in close to 60% of central cartilaginous tumors: the former is present in 50–55% with IDH2 alterations being detected in ~6% of central lesions." (PMID 28834325, 2017). "Therefore, glutaminase is higher expressed in high-grade compared to low-grade cartilage tumours but does not correlate to IDH1/2 mutation status." (PMID 29576625, 2018). "These include mutations in CTNNB1 (= beta-Catenin) in desmoid-type fibromatosis, H3-3A in conventional giant cell tumor of bone, H3-3B in chondroblastoma, IDH1/2 in cartilage tumors, KRAS and FGFR1 in non-ossifying fibroma, and GNAS in fibrous dysplasia amongst others." (PMID 38231260, 2024). "Three types of mutations caused three types of mutant IDH1 (R132C, R132G, and R132H) genes while four types of mutations causing three types of mutant IDH2 (R172S, R172T, and R172W) genes in cartilaginous tumors; however, no mutations were detected in osteochondromas or osteosarcomas." (PMID 26161668, 2015).
anaplastic gliomas (29 papers, 2011 to 2025). "Conclusions from our study also included that IDH1 mutation is a new positive prognostic factor in anaplastic gliomas, with the extent of resection being an important prognosticator." (PMID 39767640, 2024). "Additionally, it has been demonstrated that the mutational status of isocitrate dehydrogenase 1 (IDH1) in anaplastic gliomas can be predicted non-invasively using a texture analysis (TA) of diffusion-weighted imaging (DWI) in combination with conventional magnetic resonance imaging (MRI)." (PMID 37103226, 2023). "Similarly, a recent study also showed that the VASARI feature combined with ADC texture analysis could improve the accuracy of IDH1 mutation detection in anaplastic gliomas." (PMID 33553421, 2021). "In IDH1-mutant WHO grade III anaplastic gliomas, the median FMISO TBRs for AAs and AOs were 1.47 (IQR 1.42–1.70) and 1.60 (IQR 1.53–1.80), respectively." (PMID 34291337, 2021). "Although IDH1/2 mutations are scarce in primary GBM, they are common in diffuse/anaplastic gliomas and secondary GBM." (PMID 33489866, 2020). "Recently, IDH1 mutation was found to determine the prognostic and predictive value of MGMT promoter methylation in anaplastic gliomas." (PMID 25977882, 2015). "We further included data from a comparison of gene expression profiles of anaplastic glioma with or without the mutated IDH1/2 gene." (PMID 31952211, 2020). "Similarly among the recurrent tumors, IDH1/IDH2 mutation was detected in 77% (10/13) of LGGs, 61% (11/18) of anaplastic gliomas and 50% (11/22) of GBM, with 79% (11/14) of secondary GBM harbored the mutation." (PMID 23840696, 2013). "The randomized, open-label, phase 3 CATNON trial offers evidence that temozolomide adjuvant but not concurrent to a radiotherapy is associated with a survival benefit in non 1p/19q co-deleted anaplastic glioma with IDH1/2 mutation, however, not effective in IDH1/2 wildtype tumors." (PMID 38326661, 2024). "Mutations in the NADP+ dependent isocitrate dehydrogenase genes IDH1 and IDH2 are involved in the pathogenesis of a subgroup of diffuse and anaplastic gliomas." (PMID 35693015, 2022). "A recent RTOG 9402 trial has found that patients with 1p/19q non-co-deleted IDH1-mutant anaplastic gliomas have better survival after chemotherapy." (PMID 33552543, 2020). "IDH1/IDH2 mutation was observed in 90% (26/29) of primary LGGs, 38% (6/16) of primary anaplastic gliomas and none (0/8) of the primary GBM." (PMID 23840696, 2013). "In patients with anaplastic gliomas, 50% (3/6) of tumors progressing to GBM upon recurrence were IDH1 mutated and 30% (3/10) of tumors without malignant transformation upon recurrence had IDH1 mutation (p = 0.607)." (PMID 23840696, 2013). "Moreover, a distinct progression history has been seen in GBM patients, as most secondary GBMs with IDH1 mutations progressed from a WHO Grade II, whereas secondary GBMs lacking IDH1 mutations developed through progression from anaplastic gliomas, WHO Grade III." (PMID 25815458, 2015).
anaplastic oligodendroglioma (29 papers, 2013 to 2026). A WHO grade III oligodendroglioma with focal or diffuse malignant morphologic features (prominent nuclear pleomorphism, mitoses, and increased cellularity). "Tumor tissue analysis showed the lesion was an IDH1‐mutated, 1p/19q codeleted anaplastic oligodendroglioma, in line with MRS observation of elevated cystathionine and 2HG." (PMID 41290189, 2026). "In IDH1 mutated patients’ survival was markedly longer, as is in anaplastic oligodendrogliomas (with LoH 1p/19q)." (PMID 37341199, 2023). "The patient underwent craniotomy and tumor removal, and the latter turned out to be Grade III anaplastic oligodendroglioma with the IDH1 (R132H) mutation." (PMID 35777052, 2022). "The mutation of IDH1 or IDH2 genes is observed in all anaplastic oligodendrogliomas with 1p/19q codeletion, and this mutation concerns the IDH1 gene in the present case study." (PMID 31248444, 2019). "To investigate the changes in redox-active pathways induced by the IDH1 R132H mutation, we utilized a human anaplastic oligodendroglioma (HOG) cell line engineered to express either wild-type (WT) or mutant (R132H) IDH1." (PMID 29562167, 2018). "Among 12 cases of WHO grade 3 anaplastic oligodendrogliomas, 10 cases showed IDH1 mutation." (PMID 39165459, 2024). "One (9%) patient was diagnosed with anaplastic oligodendroglioma (IDH1 mutation, WHO Grade III)." (PMID 34158840, 2021). "Tmz is more tolerable than PCV, and recent clinical trials supported its use for anaplastic oligodendroglioma patients with intact 1p/19q and wild-type IDH1." (PMID 33671796, 2021). "We report a case of bone metastases from a 1p/19q codeleted and IDH1-mutant anaplastic oligodendroglioma 29 months after first diagnosis of a brain tumor." (PMID 31248444, 2019). "Based on aCGH data and limited analysis of exome sequencing, the tumor reported here has a common anaplastic oligodendroglioma genomic profile including FUBP1, CIC, and IDH1 mutations." (PMID 23527265, 2013). "The pathological diagnosis was anaplastic oligodendroglioma (WHO grade III), with IDH1:p.R132H, PIK3R1:p.G376R, CIC:p.N205S, and FUBP1:p.Y505Gfs*16 mutations confirmed as driver genes in tumor tissue." (PMID 37533228, 2023).
oligodendroglial tumor (28 papers, 2011 to 2024). Oligodendrogliomas are cerebral tumors that are differentiated from other gliomas on the basis of their unique genetic characteristics and better response to chemotherapy. "Two cases presented both IDH1 mutation and the presence of the 1p/19q codeletion; the same cases with a histopathological appearance suggestive of an oligodendroglial tumor." (PMID 36290853, 2022). "Aside from codeletion of 1p/19q, oligodendroglial tumors are strongly associated with mutations of IDH1/2, TERT promoter (TERTp) and they are also associated with methylation of MGMT and upregulation of PDGFRA." (PMID 27556304, 2016). "The IDH1 mutation of the R132H type by far outnumbers the other IDH1 mutations in diffuse astrocytic and oligodendroglial tumors." (PMID 24529257, 2014). "When analyzed by lineage, 100% (65/65) of pure oligodendroglial tumors contained IDH1/2 mutations while 64.3% and 93.3% of astrocytic and mixed lineage tumors were positive for IDH1/2 mutations, respectively." (PMID 25257301, 2014). "In oligodendroglial tumors, it is strongly associated with both IDH1/IDH2 mutations and total 1p/19q codeletion and inversely with EGFR gene amplification." (PMID 24083241, 2013). "All mutations affected codon R132 of the IDH1 gene, with the exception of one oligodendroglial tumor with mutation at codon R172 of the IDH2 gene." (PMID 24083241, 2013). "The IDH1 mutation c.395G>A (R132H) was present in 14 of the 17 oligodendroglial tumors, including all twelve tumors with 1p/19q co-deletion and two tumors of the “astrocytic” genetic subtype." (PMID 24086756, 2013). "In oligodendroglial tumors, it was strongly associated with both IDH1/IDH2 mutations and total 1p/19q codeletion and inversely with EGFR gene amplification." (PMID 24083241, 2013). "For oligodendroglial tumors, however, the incidences of IDH1/2 mutation between different sides of the brain (84.8%, 75.8% and 100.0%, respectively) were not significantly different." (PMID 22427879, 2012). "The incidence of IDH1/2 mutation in oligodendroglial tumors of the frontal origin (92.7%) was significantly higher than that of non-frontal origin (66.7%) (P = 0.005)." (PMID 22427879, 2012). "The incidence of IDH1/2 mutation in oligodendroglial tumors of the temporal origin (40.0%) was significantly lower than that of non-temporal origin (88.5%) (P = 0.001)." (PMID 22427879, 2012). "Furthermore despite the high frequency of IDH1 p.R132H mutations detected in oligodendroglial tumors, we found that 13.6% (6/44) of O2s had IDH2, IDH1 p.R132G or IDH1 p.R132S mutations." (PMID 25257301, 2014). "EMP3 promoter hypermethylation is significantly associated with IDH1/IDH2 mutations in both astrocytic and oligodendroglial tumors." (PMID 24083241, 2013). "Mutation of the isocitrate dehydrogenase enzyme isoform 1 (IDH1 R132) and 2 (IDH2 R172) is associated with a large proportion of diffuse astrocytic and oligodendroglial tumors." (PMID 24179531, 2013). "In 71 oligodendroglial tumors (Grade II and III), the mean global incidence of IDH1/2 mutation was 81.7%." (PMID 22427879, 2012). "In anaplastic oligodendroglial tumors, IDH1 mutation are prognostic for overall survival but not predictive for outcome to PCV chemotherapy." (PMID 32547876, 2020).
oligodendroglial tumor (continued). "Interestingly, there is a subset of anaplastic oligodendroglial tumors characterized by 1p19q loss of heterozygosity (LOH) and IDH1 mutations that significantly benefits from procarbazine, CCNU, and vincristine (PCV) chemotherapy." (PMID 24984002, 2014). "Even if the “classic profile” was not prevalent (∼15%) in AO, as compared to the proneural one (∼75%), this subclass allowed to distinguish oligodendroglial tumors with neither 1p/19q co-deletion nor IDH1 mutations but with EGFR gene amplification and chromosome 10 loss." (PMID 23874590, 2013).